CA9 (carbonic anhydrase 9)
Diseases named in the same sentence as CA9 in open-access papers (continued):
Sharing a sentence is not in itself a finding about the gene and the disease.
tumor (1,367 papers, 1999 to 2026). "The study also assessed carbonic anhydrase IX (CA9), an enzyme involved in pH regulation and cell survival commonly associated with tumor progression." (PMID 41226317, 2025). "CA9 is consistently elevated in UC tissues compared to benign urothelium and is strongly associated with tumor grade, stage, and prognosis." (PMID 41467176, 2025). "High expression of CA9 is positively correlated with a higher risk of disease progression and metastases developing, independently of tumor type or site, and is a predictive marker for radio- and chemotherapy resistance." (PMID 41516250, 2025). "Clinically, this implies that while LST1 reflects chronic inflammatory activation, it achieves greater diagnostic discrimination when combined with tumor-specific markers such as CA9, PBRM1, and HLA-exhaustion signatures." (PMID 41488617, 2025). "Markers such as GLUT-1, HIF-1α, FASN, LAT-1, and CA9 have been associated with tumor aggressiveness, metastasis, and poor prognosis, particularly in PanNENs." (PMID 41458541, 2025). "Given their essential roles in regulating pH balance and tumor association, substantial efforts have been made to generate specific CA inhibitors (CAi) against two membrane associated CA isoforms—CA9 and CA12 as anticancer therapy for the last two decades." (PMID 38530845, 2024). "Carbonic anhydrase (CA) is a large class of zinc metalloenzymes, and the transmembrane protein CA9 is one of the known tumor‐associated CA isozymes." (PMID 36537608, 2023). "Car9 encodes carbonic anhydrase 9, an enzyme critical for extracellular acidification and matrix remodeling, thereby enhancing the metastatic potential of the tumor cells." (PMID 37834315, 2023). "One of the most well-known genes linked to hypoxia in tumor cells is CA9, which is rapidly and significantly increased in hypoxic environments." (PMID 37958210, 2023). "Of those not in the seed gene list, the well-known hypoxia-associated CA9 was the fifth most significantly up-regulated gene in the 140-tumour group." (PMID 35079065, 2022). "CA9 is over-expressed in many epithelial neoplasms and has been linked to tumour hypoxia and carcinogenesis." (PMID 36415514, 2022). "CA9 appears to be involved in tumor growth and metastatic dissemination in vitro and clinical studies, and overexpression of CA9 is linked to a poor prognosis in a variety of cancers." (PMID 35440019, 2022). "Carbonic anhydrase 9 (CAIX) is a transmembrane protein and is one of only two tumor-associated carbonic anhydrase isoenzymes known." (PMID 34977339, 2022). "We targeted CA9, a cell-surface enzyme associated with remodeling the tumor pH environment, and integrin-α11β1, a cell-surface heterodimeric receptor involved in cancer-associated fibroblast biology." (PMID 33980972, 2021). "Using mouse NB cisplatin-treated xenografts, we identified two genes within the list associated to the malignant stage (MCM2 and carbonic anhydrase 9), whose expression is positively correlated with tumor growth." (PMID 33153038, 2020). "This associated with reduced tumor hypoxia, assessed by staining for CA9 upon glufosinate treatment, altogether suggesting increase blood vessel functionality." (PMID 32885605, 2020). "Of note, the HIF target and hypoxic tumor hallmark gene carbonic anhydrase 9 (CA9) was identified among the upregulated genes, which confirms the hypoxic culture conditions." (PMID 33142239, 2020). "It is concluded that CA9 is a marker strongly associated with FOXP3+ regulatory T-cell abundance in the tumour environment of NSCLC." (PMID 32066909, 2020). "CA9 expression by cancer cells is associated significantly with FOXP3+ regulatory T-cell abundance in the tumour stroma of NSCLC." (PMID 32066909, 2020). "The CA9 mRNA level in tumor tissue samples was significantly higher compared to tumor-associated normal tissue samples in this study cohort." (PMID 30654595, 2019).
tumor (continued). "In the current study, we found that CA9, the expression of which is also associated with tumor hypoxia, was expressed at significantly higher levels in patients with higher HMCN1 VAFs than in those with lower VAFs." (PMID 30279964, 2018). "Human antibodies specific to several tumor targets were used in that study, including anti-mesothelin and MN-antigen (a tumor associated antigen carbonic anhydrase IX, CA9)." (PMID 28574434, 2017). "A recent study reported that carbonic anhydrase IX (CA9), which modulates tumor-associated cell migration and invasion, interacts with DKK-1." (PMID 28938611, 2017). "Both NHE1 and CA9 have indeed been implicated in a number of studies regarding the migratory/invasive capacity of tumor cells suggesting a role in cell adhesion processes." (PMID 28055960, 2017). "High miR-210 was significantly associated with high HIF-1α protein (P=0.001), CA9 protein (P=0.0004), Glut-1 protein (P=0.001), 26-gene hypoxia score (P=0.007), tumour necrosis (P=0.02) and concurrent pTis (P=0.03)." (PMID 27441495, 2016). "Bevacizumab-induced reductions in tumour perfusion were significantly associated with increased HIF1α or CA9 expression in primary liver cancer." (PMID 25700172, 2015). "CA9 is presumed as one of the most prominent markers of tumor hypoxia with potential to serve as a diagnostic biomarker, prognostic indicator as well as tumor therapeutic target in many cancers." (PMID 26447758, 2015). "Second, our data provide novel features on the comparative diagnostic efficacy of the second tested tumor-specific marker of CA9." (PMID 24527437, 2014). "Similar data revealed associations of tumor responsiveness between high CA9 expression and anti-VEGF therapy agents such as sunitinib, sorafenib, bevacizumab, temsirolimus and vatalanib." (PMID 24086736, 2013). "It was reported that CA9 as a marker of hypoxia and it is also associated with the tumor grade, metastasis and patients prognosis." (PMID 24349364, 2013). "In the present study, a significantly higher distribution frequency of Invasive tumor stage was exhibited in UCC patients with at least 1 polymorphic A allele of CA9 rs1048638 compared to those with the WT genotype." (PMID 24349364, 2013). "Previous studies demonstrated that CA9 expression represents biologic tumor aggressiveness and is associated with poor clinical outcomes in several tumors including head and neck, cervix, kidney, and lung cancers." (PMID 23226559, 2012). "A tumor-associated carbonic anhydrase MN/CA9 (MN) gene is also activated by transcription factor AP1." (PMID 22573138, 2012). "The aberrant expression of CA9 was observed in cancer cells themselves or tumor-associated stromal tissues in OSCC patients and correlated with a poor prognosis and nodal metastasis." (PMID 23226559, 2012). "In tumor tissues, CA IX is linked with the hypoxic phenotype mediated by the hypoxia-inducible transcription factor 1 (HIF-1), which binds to the hypoxia responsive element, HRE, of the CA9 promoter." (PMID 20573196, 2010). "The presence of hypoxia-associated endogenous proteins, such as HIF-1α and CA9, and pimonidazole, an exogenous marker, indicated that both tumour types had hypoxic loci." (PMID 20145613, 2010). "Nonetheless, we noted that improved PFS was associated with lower CA9 expression as a marker of tumour hypoxia." (PMID 19920819, 2009). "We demonstrate that the AS variant is less abundant than the full-length (FL) CA9 mRNA in tumours, but in contrast, can be detected in normal tissues and under normoxia." (PMID 18026188, 2008). "In terms of IHC score, CA9 expression was significantly associated with tumour staging and poor prognosis." (PMID 18841153, 2008). "The value of membranous CA9 was underlined by its strong associations with factors of poor outcome (tumour size and differentiation), but especially with a shorter survival (P=0.0004)." (PMID 15558070, 2005).
tumor (continued). "This tumour-associated distribution of CA IX is related to a strong transcriptional activation of the CA9 gene by a hypoxia-inducible factor 1, a key mediator of the molecular responses to low oxygen supply." (PMID 16278664, 2005). "Recently, we extended the range of HIF-1 target genes by identifying the two tumour-associated transmembrane carbonic anhydrases (CA) CA9 and CA12 as upregulated by hypoxia in a range of epithelial cancer cell lines." (PMID 12671706, 2003). "Carbonic anhydrase (CA)-9 is one of the best-known genes associated with tumour cell hypoxia, and is quickly and extensively upregulated under hypoxic conditions." (PMID 12865916, 2003). "Carbonic anhydrases are important for regulation of pH and we demonstrated recently that the tumour associated carbonic anhydrase 9 (CA9) is tightly regulated by the HIF-1 pathway." (PMID 11953885, 2002). "An acidic tumor microenvironment is associated with hypoxia; hypoxic solid tumors undergo metabolic alterations and upregulate acid efflux mechanisms mediated by CA9, among others, thereby leading to extracellular acidification." (PMID 40873634, 2025). "Furthermore, given the high expression of CA9 in RCC tumours secondary to VHL loss and constitutive HIF activation, GPR65 represents a rational therapeutic target in this disease context." (PMID 41375084, 2025). "CA9 has been associated with hypoxia and poor prognosis in a range of tumor types." (PMID 38016355, 2024). "It has also reported that CA9 is associated with tumor invasion and metastasis." (PMID 39471162, 2024). "Therefore, targeting tumor-associated CAs, especially CA9, is now considered a pertinent approach for the development of new cancer therapeutics to treat hypoxic tumors." (PMID 35362480, 2022). "In turn, the antiproliferative effect of Indisulam may be caused by dysregulation of cellular pH after inhibition of CA9, making the tumor more sensitive to external agents." (PMID 36672576, 2022). "Inhibition of tumor-associated CA9 is useful in the management of hypoxic tumors that do not respond to classic chemotherapy or radiotherapy, and many types of highly effective CA9 inhibitors have been developed and evaluated in vitro." (PMID 35362480, 2022). "Here we propose that CA9 is an important tumor associated antigen that may be exploited using this strategy." (PMID 35874663, 2022). "The multivariate Cox’s regression hazard analysis (adjusted to the patient’s tumor stage, lymph node status (N-stage) and tumor grade), showed an increased risk of death (RR = 2.2; p = 0.02) for patients with a high CA9 mRNA level in their tumors as compared to patients with a low CA9 mRNA level." (PMID 30654595, 2019). "In addition, multivariate Cox’s regression analysis (adjusted to the patient’s tumor stage, lymph node status (N-stage) and tumor grade) revealed that a high CA9 mRNA level in the tumor is associated with an increased risk of locoregional recurrence." (PMID 30654595, 2019). "In contrast, CA9 was detected in association with the membranes of tumor cells." (PMID 30863491, 2019). "CA9 has been implicated in the regulation of the micro-environmental pH in tumor hypoxia." (PMID 24893880, 2014). "Therefore, the inhibitor or regulatory proteins of hypoxic tumor-associated CA9 possesses the potential therapeutic possibility for those tumors in which CA9 is involved in perturbing the extra- or intra- tumoral acidification process." (PMID 23394073, 2013). "Immunohistochemistry for the HIF1α-inducible proteins CA9 and Glut1, and for HIF1α itself, revealed moderate or strong expression of at least one of these markers in all but two of the tumours, verifying the well-described hypoxic signature associated with loss of function of pVHL." (PMID 23606570, 2013). "Thus, an inhibitor of hypoxic tumor-associated CA9 expression offers therapeutic potential in the treatment of tumors in which CA9 is contributes to the perturbation of the extra- or intra-tumoral acidification process." (PMID 23671581, 2013).
tumor (continued). "Immunohistochemical analysis based on hypoxia-associated endogenous proteins such as HIF-1, CA9, or pimonidazole, an exogenous marker that is preferentially trapped in hypoxic cells, can yield tumour hypoxia information with direct comparison to histologic findings." (PMID 20145613, 2010). "Hypoxia is one of driving forces of tumor angiogenesis; therefore, expression of the hypoxia-inducible enzyme, CA9, might be associated with the outcome of antiangiogenic treatment." (PMID 19619339, 2009). "However, the most frequently reported studies associating CA9 expression with tumor behavior have been in patients with clear cell type renal cell carcinoma (RCC)." (PMID 19619339, 2009). "However, expression of only HIF2α and CA9 in the tumour-associated stroma was correlated with a poorer prognosis, suggesting that tumours with this particular phenotype follow a more aggressive course." (PMID 18728663, 2008). "Exclusive nuclear FIH-1 expression was significantly inversely associated with tumour grade (P = 0.02) and risk of recurrence (P = 0.04), whereas exclusive cytoplasmic FIH-1 was significantly positively associated with tumour grade (P = 0.004) and carbonic anhydrase 9 expression (P = 0.02)." (PMID 18096060, 2007). "In advanced PETs, low MVD associated with an increase in tumour-cell proliferation may, beyond the limit of oxygen diffusion, lead to hypoxia and activation of CA9." (PMID 15558070, 2005). "High tumour cell proliferation involves increased oxygen consumption, leading to oxygen deficiency and hypoxia-modulated gene expression, including activation of vascular endothelial growth factor and CA9 gene transcription by Hif-1α." (PMID 16251878, 2005). "Furthermore, retrospective analysis of HNSCC patient samples treated with immunotherapy either as front-line therapy or following platinum failure found that patients, with higher %CA9/mean intensity (%CA9/I) associated with more hypoxic tumours, had reduced efficacy of anti-PD-1 therapy." (PMID 38352889, 2024). "Moreover, CA9 expression potentially contributes to the regulation of cancer cell differentiation and mediates tumour‐associated genes and signalling pathways, including apoptosis, hypoxia, G2M checkpoint, PI3K/AKR/mTOR signalling and TGF‐beta signalling pathways." (PMID 32299152, 2020). "Previous studies have shown that CA9 is predominantly associated with and high expressions in many human tumor types, including breast, lung, kidney, cervix uteri, oral cavity, brain, pancreas, and gastric epithelium; but its decreased expression may be associated with human gastric carcinogenesis." (PMID 26447758, 2015). "Several well known regulated (and cancer associated) genes (e.g. VEGFA, CA9) are already known to be alternatively spliced, although the relationship between hypoxia, differential transcript expression, alternative splicing, and tumour phenotype has yet to be fully determined." (PMID 19936049, 2009). "Using a computational strategy based on CA9 expression as a surrogate of HIF activity, we identified Ubiquitin-Specific Protease 29 (USP29) as a key regulator associated with hypoxia and tumour progression and severity in PCa." (PMID 42125859, 2026). "Taken together, our findings suggest that dysadherin expression regulates CA9 expression across multiple cancer types, highlighting its role in tumor adaptation to the acidic TME." (PMID 41535258, 2026). "Overall, our results suggest that the dysadherin/CA9 axis promotes adaptation to acidic microenvironments, thereby enhancing tumor growth and metastatic potential (graphic summary)." (PMID 41535258, 2026). "CA9, upregulated by hypoxia, contributes to an acidic environment supporting tumor growth, a more aggressive GBM phenotype, and treatment resistance." (PMID 41883712, 2026). "Clonogenic and tumor formation assays revealed that dysadherin KO reduced cell survival and tumor formation under acidic conditions, whereas CA9 OE reversed these effects." (PMID 41535258, 2026).
tumor (continued). "Overall, our study demonstrated that tumor cells with a highly active dysadherin/CA9 axis exploit acidosis to drive malignancy." (PMID 41535258, 2026). "Positive staining for carbonic anhydrase 9 (CAIX) was used to define tumor cells, as it is a well-characterized marker of hypoxia and is commonly upregulated in RCC cells." (PMID 40440354, 2025). "In the RM+ group under 2D conditions, tumour suppressor genes, CDKN1A and NR4A3, were upregulated and tumour-promoting genes, CA9, EFNA1, and SUSD2, were downregulated." (PMID 41381717, 2025). "RNA sequencing revealed upregulation of tumour suppressor genes, including CDKN1A and NR4A331,32, and downregulation of tumour-promoting genes, including CA9, EFNA1, and SUSD233–36." (PMID 41381717, 2025). "These assays revealed the tumor cells in the cerebellar lesion showed expression of PAX8 along with focal expression of CA9 (23.7%) and CD10 (4.4%)." (PMID 39833894, 2025). "Collectively, antitumor efficacy test in H22 subcutaneous tumor model confirmed that HBO suppressed pH‐regulatory genes such as CA9, regulated tumor pH, and augmented therapeutic effects of HHD‐Cu NPs." (PMID 40873634, 2025). "The RCC-derived tumours demonstrated high CA9 expression, and a high LDHA-to-LDHB expression ratio (>3:1) by transcriptomics." (PMID 41375084, 2025). "CA9, a transmembrane zinc metalloprotease with cell adhesion functions, is crucial for tumor growth and survival." (PMID 40723784, 2025). "Carbonic anhydrase IX (CA9), a biomarker of tumor invasion, exerts a significant regulatory role in modulating this acidic TME." (PMID 40165895, 2025). "Hypoxia is a critical feature of the PanNET tumor microenvironment, influencing the expression of markers such as carbonic anhydrase 9 (CA9), which is induced by HIF-1α." (PMID 41458541, 2025). "HBO overcomes tumor hypoxia, downregulates pH‐regulatory proteins such as CA9, and leads to intracellular accumulation of acidic metabolites." (PMID 40873634, 2025). "To address the need for early detection, we developed a rapid point of care LFA for CA9 released by BIA-ALCL tumor cells." (PMID 40723287, 2025). "CA9 is a transmembrane zinc metalloenzyme that plays a central role in tumour acidification by catalysing the reversible hydration of CO2 to bicarbonate and protons at the cell surface." (PMID 41375084, 2025). "Exosomal biomarkers such as miR-2276-5p (OC), miR-141-3p (RCC), and tumor-specific surface markers (e.g., CD147, CA9, CD70) are emerging as key diagnostic tools." (PMID 40303340, 2025). "TNC colocalizes with the hypoxia marker carbonic anhydrase 9 (CA9) in tumor tissues, indicating its involvement in the tumor response to hypoxia." (PMID 40046232, 2025). "ROS-Gels respond to the postoperative tumor microenvironment, continuously releasing drugs to inhibit TLR9/CA9 and block the tumor-hypoxia vicious cycle." (PMID 41142962, 2025). "CA9‐mediated dysregulation of tumor pH promotes tumor progression through various mechanisms, including the induction of immune suppression, reduced intercellular adhesion, enhanced tumor cell proliferation, and promotion of self‐renewal and stemness of CSCs." (PMID 40873634, 2025). "Numerous studies indicate a correlation between hypoxia‐related proteins like HIF‐1α and CA9 as well as the stemness of tumor cells." (PMID 40873634, 2025). "CSCs, widely blamed as the primary cause of tumor recurrence, metastasis, and treatment resistance, exhibit higher CA9 expression and stronger survival capabilities in dysregulated tumor acidic pH than bulk cancer cells." (PMID 40873634, 2025). "CA-9 is one of the most important proteins promoting different phases of cancer development, which is overexpressed in response to tumor hypoxia in many cancers." (PMID 41515132, 2025). "The overexpression of CA9 is seen in different tumor types including breast, renal, and intracranial tumors, and is associated with poor prognosis." (PMID 39858084, 2025).